TET1 (tet methylcytosine dioxygenase 1)
Diseases named in the same sentence as TET1 in open-access papers (continued):
Sharing a sentence is not in itself a finding about the gene and the disease.
Hepatic steatosis (4 papers, 2020 to 2025). Steatosis is a term used to denote lipid accumulation within hepatocytes. "Since TET1 had been previously shown to be inhibited in both in vivo and in vitro NAFLD models, we then explored the role of complete deficiency of TET1 (TET1 knockout) in hepatic steatosis." (PMID 32577122, 2020). "Given the previous finding that TET2 and TET3 liver specific KO promoted fatty liver development in mice, we decided to investigate the role of TET1 in hepatic steatosis." (PMID 40164757, 2025). "Their degree of liver steatosis was more severe than that of wild-type mice, suggesting that TET1 had a significant protective effect against NAFLD." (PMID 32577122, 2020). "Histological analysis revealed decreased hepatic steatosis in the TET1 i treated group." (PMID 40164757, 2025). "In order to study how the lack of TET1 aggravates fatty liver caused by HFD, we first investigated several key regulators in the process of fat production." (PMID 32577122, 2020). "The knockout of TET1 could aggravate hepatic steatosis compared with WT mice, which was consistent with body weight, intrahepatic triglyceride (TG), serum TG, cholesterol, aspartate aminotransferase (AST) and alanine aminotransferase (ALT), all of which were significantly higher in TET1−/− mice." (PMID 32577122, 2020).
hyperglycaemia (4 papers, 2020 to 2024). "Our data identified that hyperglycemia drove O-GlcNAcylation of the protein TET1 via OGT-catalyzed activity." (PMID 37231419, 2023). "The studies conducted in this report indicated that hyperglycemia impacts CSC induction in TNBC via OGT-dependent glycosylation of TET1." (PMID 37231419, 2023). "Glucose flux leads to increased O-GlcNAcylation via the hexosamine biosynthetic pathway, offering a potential connection between hyperglycemia and TET1 target gene expression." (PMID 37231419, 2023). "AKG treatment in hyperglycemia-exposed H9c2 cells also showed a similar reversal of global 5mC and 5hmC deposition, possibly by improving TDG function and its association with TET1 to complete the DNA demethylation cycle." (PMID 37101286, 2023). "Using inhibitors, RNA silencing, and overexpression engineering, we determined a potential hyperglycemia-promoted mechanism for upregulated OGT levels in TNBC that involves TET1." (PMID 37231419, 2023). "Gadd45β promotes DNA demethylation of PGC‐1α promoter in binding with TET1, thereby stimulating PGC‐1α expression to promote gluconeogenesis and hyperglycaemia." (PMID 39653679, 2024).
Hypertension (4 papers, 2011 to 2025). The presence of chronic increased pressure in the systemic arterial system. "The TET-1 mice, which overexpress ET-1 specifically in the endothelial cells of small arteries, developed hypertension." (PMID 22096514, 2011). "As a result, the expression of DNA methyltransferases DNMT1, 3 A, and 3B and DNA demethylation enzymes TET1 and 3, after correction for AQP1, increased in patients with hypertension." (PMID 32099032, 2020). "In addition, the expression of DNA methyltransferases DNMT1, 3 A, and 3B and DNA demethylation enzymes TET1 and 3, after correction for SGLT2, increased in patients with hypertension." (PMID 32099032, 2020). "Aberrant methylation due to loss of TET1 may be responsible for several malignancies, while low levels of TET1 were identified in several non-malignant diseases like polycystic ovary syndrome and hypertension." (PMID 40427015, 2025).
infertile (4 papers, 2016 to 2023). "TET1 expression in infertile women with a mild and advanced form of the disease was lower than in the fertile control group." (PMID 35409163, 2022). "In order to identify the dairy goat mGSC characteristics and whether Tet1 effects on the fate of mGSCs, we transplantated mGSC-pCDH and mGSC-pCDH-mTet1 cells into infertility mouse testes treated with busulfan." (PMID 27857213, 2016).
intrahepatic cholangiocarcinoma (4 papers, 2019 to 2025). A carcinoma that arises from the intrahepatic bile duct epithelium in any site of the intrahepatic biliary tree. "In contrast, TET1 expression was decreased in intrahepatic cholangiocarcinoma." (PMID 40599235, 2025). "TET1 decreases in intrahepatic cholangiocarcinoma (ICC) and suppresses ICC progression by activating oncogenes through direct binding to oncogene promoters for demethylation." (PMID 34656178, 2021).
leiomyoma (4 papers, 2016 to 2025). A well-circumscribed benign smooth muscle neoplasm characterized by the presence of spindle cells with cigar-shaped nuclei, interlacing fascicles, and a whorled pattern. "In the context of leiomyoma, this is consistent with the authors findings that leiomyoma stem cells are associated to TET1 low transcripts levels, and thus to rather high methylation." (PMID 33156897, 2020). "Both H19 and TET1, a key regulator of DNA methylation, were identified to be strong predictive markers for postoperative recurrence of fibroids, suggesting that levels of H19 and TET1 could potentially be used as diagnostic/predictive markers." (PMID 40862769, 2025). "Small interfering RNA (siRNA) knockdown of either TET1 or TET3 leads to decreased proliferation of primary leiomyoma cells, suggesting a potentially important role of TETs in the pathogenesis of fibroids." (PMID 31089260, 2019). "Furthermore, TET1 and TET3 protein levels are higher in uterine leiomyoma, and TET1 or TET3 knockdown decrease cell proliferation of leiomyoma cells." (PMID 27557497, 2016).
lymph node metastasis (4 papers, 2015 to 2023). "Low TET1 expression correlated with local invasion, lymph node metastasis and TNM stage (p<0.05)." (PMID 27121319, 2016). "Here, we show that tumors with regional lymph node metastases (pN+) exhibited decreased expression of DNMT1, 3A and 3B, and TET1 and 3 compared to non-metastatic tumors (pN0), suggesting that metastasis requires a distinct expression profile of DNA methyltransferases/demethylases in solid tumors." (PMID 37367043, 2023).
T-cell acute lymphoblastic leukemia (4 papers, 2019 to 2025). Acute lymphoblastic leukemia of T-cell origin. "Interestingly, TET1 is found to be crucial for the proliferation of human T-cell acute lymphoblastic leukemia, suggesting context-dependent roles of TET1/Tet1 in leukemogenesis." (PMID 33705482, 2021). "Poole et al49 demonstrated the contrasting roles of TET1 and TET2 in T-cell acute lymphoblastic leukemia." (PMID 40520993, 2025).
type 2 diabetes (4 papers, 2018 to 2024). "It suggests that the alteration of TET1 mRNA and TET1 protein expression levels can be a biomarker for the development of type 2 diabetes." (PMID 30574144, 2018). "Further studies are required to clarify the signaling axis effects and analyze the protein structure of TET1 targeting SIRT1, providing more precise targets for the clinical therapy to type 2 diabetes or metabolism-related diseases." (PMID 34738906, 2021). "For example, individuals with type 2 diabetes had higher DNMT3B levels in cultured myotubes and decreased TET1 expression in adipose tissue vs tissue from individuals without type 2 diabetes, while palmitate exposure decreased DNMT3A and DNMT1 expression in human pancreatic islets." (PMID 35307762, 2022).
bladder (3 papers, 2019 to 2021). "TET1 was recurrently mutated across multiple cancers and more frequently seen in skin, lung, gastrointestinal, and urogenital cancers." (PMID 31623662, 2019). "Comparison of PCa specimens with regard to Gleason scores revealed 7 CpG sites in TET1 (2 in the promoter and 5 in the gene body) to be significantly hypermethylated or hypomethylated in the course of prostate carcinogenesis." (PMID 34844636, 2021). "Herein we sought to determine whether TET1 acts a critical role in bladder carcinogenesis and whether the increase of TET1 activity by vitamin C can suppress tumorigenicity." (PMID 32528872, 2020).
childhood asthma (3 papers, 2019 to 2022). "Traffic-related air pollution exposure increased locus-specific methylation in the TET1 promoter region, specifically at CpG (cg23602092) site, which was significantly associated with childhood asthma." (PMID 32047643, 2019). "Our studies in pediatric nasal epithelial samples and bronchial epithelial cells (HBECs) suggest that Tet1 (Tet Methylcytosine Dioxygenase 1) may regulate childhood asthma and responses to environmental exposures." (PMID 35627266, 2022). "Previous studies have suggested a role for Tet1 in the pathogenesis of childhood asthma." (PMID 31089182, 2019).
diffuse large B-cell lymphoma (3 papers, 2019 to 2025). "Augmented expression of circ-APC inhibited the growth of diffuse large B-cell lymphoma (DLBCL) cells in vitro and in vivo by recruiting TET1 to the promoter of APC, subsequently resulted in the activation of canonical Wnt/β-catenin signaling pathway." (PMID 33069241, 2020). "In diffuse large B-cell lymphoma (DLBCL), the downregulation of circAPC implied sponging of miR-88 and activation of the oncogene, TET1, ultimately suppressing the Wnt/β-catenin pathways and promoting cell proliferation." (PMID 40565526, 2025).
gestational hypertension (3 papers, 2017 to 2023). "Other researchers noted that fumaric acid and succinic acid may treat gestational hypertension by downregulating the expression of ten-eleven translocation 1 (TET1) and calcium-activated potassium channel subunit β1 (KCNMB1)." (PMID 35335911, 2022). "Therefore, we hypothesized that TET1 activation by hypoxia is necessary for placentation during early pregnancy and that TET1 depletion may contribute to preeclampsia." (PMID 28808304, 2017).
head and neck squamous cell carcinoma (3 papers, 2018 to 2023). A squamous cell carcinoma that arises from any of the following anatomic sites: lip and oral cavity, nasal cavity, paranasal sinuses, pharynx, larynx, and salivary glands. "DACT, WNT5A, and WNT7B were significantly positive correlation with TET1(p < 0.05), and WNT4 and WNT7A were negative correlation with TET1 in the TCGA Head and Neck Squamous cell Carcinoma database (p < 0.05)." (PMID 30075814, 2018).
holoprosencephaly (3 papers, 2021 to 2023). Holoprosencephaly (HPE) is a complex brain malformation resulting from incomplete cleavage of the prosencephalon, occurring between the 18th and 28th day of gestation, and affecting both the forebrain and face, which results in neurological manifestations and facial anomalies of variable severity. "However, the double knockout of Tet1/Tet2 or Tet1/Tet3 respectively causes exencephaly and holoprosencephaly in some embryos." (PMID 35163133, 2022). "However, combined loss of TET1/2 and TET1/3 causes exencephaly and holoprosencephaly in some embryos, respectively suggesting redundancy between TETs in neurogenesis that warrants further investigation." (PMID 33681230, 2021). "Similarly, combined loss of TET1 and TET3 leads to early developmental arrest and holoprosencephaly." (PMID 33681230, 2021).
Hypercholesterolemia (3 papers, 2020 to 2022). An increased concentration of cholesterol in the blood. "For example, hypercholesterolemia causes Tet1 downregulation in hematopoietic stem cells and leads to the upregulation of p19, p21 and p27 by decreasing the H3K27me3 repressive mark of these genes." (PMID 35456045, 2022). "Taken together, our results indicate that hypercholesterolemia downregulates the expression of Tet1 in HSCs which, in turn, increases the expression of p19 and p21." (PMID 32107419, 2020). "This study demonstrates that TET1 plays a critical role in maintaining the quiescence and reconstitution capacity of HPSCs and that hypercholesterolemia accelerates the HPSC aging phenotype by decreasing TET1 expression." (PMID 32645995, 2020). "Here, we show that hypercholesterolemia decreased the expression of Tet1 in HSCs and subsequently upregulated the expression p19 and p21 by reducing repressive H3K27me3." (PMID 32107419, 2020). "PCR analysis showed that Tet1 deficiency and hypercholesterolemia did not change the expression of HSC markers, including CD34, Sca-1 and cKit." (PMID 32107419, 2020). "We found that hypercholesterolemia downregulates Ten eleven translocation 1 (Tet1) in HSCs." (PMID 32107419, 2020).
medulloblastoma (3 papers, 2017 to 2021). A malignant, invasive embryonal neoplasm arising from the cerebellum. "We demonstrate that both 5caC enrichment and elevated TET1 expression are observed in SHH medulloblastomas and ependymomas." (PMID 28228863, 2017). "High TET1 levels correlating with Tet-dependent activity are observed in medulloblastoma and EPN cell lines, suggesting an involvement of TET1 in the pathogenesis of these hindbrain tumors." (PMID 34885210, 2021). "In the present study, we aimed to determine the global levels and nuclear distribution of oxi-mCs as well as the expression of TET1/2/3 and TDG transcripts in tumour cell lines derived from paediatric medulloblastomas and ependymomas." (PMID 28228863, 2017).
memory impairment (3 papers, 2020 to 2025). "Given that TET1 has been previously associated with learning and memory impairments in mice, and NONO has been shown to be a major component of the TET complex, we therefore hypothesized that NONO and TET1 collaborate to enable appropriate neuronal gene regulation." (PMID 32286661, 2020).
metabolic dysfunction-associated steatotic liver disease (3 papers, 2022 to 2025). Metabolic dysfunction-associated steatotic liver disease (MASLD, formerly known as nonalcoholic fatty liver disease or NAFLD) is a type of liver disease that is not caused by alcohol. "Liver TET1 was found to promote metabolic dysfunction-associated steatotic liver disease (MASLD) by regulating CD36 expression, suggesting TET1 as a therapeutic target for MASLD treatment." (PMID 40164757, 2025). "Wang et al108 found that TET1 played a protective role against non-alcoholic fatty liver disease by promoting fatty acid oxidation through the activation of the peroxisome proliferator-activated receptor alpha (PPARα) pathway." (PMID 40520993, 2025). "TET1 was found to bind directly to the promoter of PPARα and increase its hydroxymethylation level, ultimately inhibiting the progression of non-alcoholic fatty liver disease." (PMID 40520993, 2025). "TET1 has been reported to inhibit the progression of nonalcoholic fatty liver disease by hydroxymethylation of the PPARα promoter." (PMID 36195596, 2022).
nasopharyngeal carcinoma (3 papers, 2018 to 2021). A carcinoma arising from the nasopharyngeal epithelium. "Recent studies revealed that TET1 could induce the demethylation on the promoters of a few Wnt antagonists and restore their expressions in nasopharyngeal carcinoma, finally decreasing the expression of nuclear β-catenin." (PMID 32528872, 2020). "Additionally, in nasopharyngeal carcinoma (NPC) cells, overexpression of TET1 suppresses cell growth of NPC and significantly inhibits the expression of β-catenin." (PMID 34926132, 2021). "However, whether TET1 plays any role in nasopharyngeal carcinoma (NPC) remains unclear." (PMID 30075814, 2018).
osteoarthritis (3 papers, 2022 to 2023). A noninflammatory degenerative joint disease occurring chiefly in older persons, characterized by degeneration of the articular cartilage, hypertrophy of bone at the margins and changes in the synovial membrane. "Decreased levels of TET1 accompanied by increased levels of 5hmC have been observed in chondrocytes from patients suffering osteoarthritis due to the minor conversion of 5hmC to 5fC or 5caC." (PMID 36675131, 2023). "To understand the role of TET family proteins in RA progression, we first analyzed the expression profiles of the TET1/2/3 proteins, 5mC, and 5hmC in the synovial membranes of RA patients, and compared these with those of osteoarthritis (OA) patients." (PMID 36114544, 2022).
pancreatic ductal adenocarcinoma (3 papers, 2023 to 2025). An infiltrating adenocarcinoma that arises from the epithelial cells of the pancreas. "TET1 has been shown to overcome chemotherapy resistance in pancreatic ductal adenocarcinoma by reducing the activity of the cell adhesion molecule L1 like (CHL1)-associated Hedgehog signaling pathway." (PMID 40520993, 2025). "Consequently, patients with elevated TET1 levels tend to have a more favorable prognosis in pancreatic ductal adenocarcinoma cases." (PMID 40520993, 2025). "Previous study reported that enhanced RBP TET1 expression could sensitize pancreatic ductal adenocarcinoma cells to 5FU and gemcitabine through inhibiting the CHL1-related Hedgehog signalling pathway." (PMID 36895014, 2023).
seminoma (3 papers, 2013 to 2024). A radiosensitive malignant germ cell tumor found in the testis (especially undescended), and extragonadal sites (anterior mediastinum and pineal gland). "Our finding of TET1 overexpression in seminomas implicates the role of 5-hmC in transcriptional derepression." (PMID 28302141, 2017). "The deeply hypomethylated genome of seminoma cells has been recently correlated with elevated expression of the TET1 enzyme in GCTs." (PMID 28302141, 2017). "A positive correlation between PRAME and TET1 expression was seen in seminomas." (PMID 38541782, 2024). "Seminoma and EC cell lines and tumors display most prominent expression of TET1 while TET2 and TET3 are expressed at very low levels, suggesting that here TET1 is the main molecule involved in 5mC oxidation." (PMID 24386123, 2013).